FLNA (filamin A)
Diseases named in the same sentence as FLNA in open-access papers (continued):
Sharing a sentence is not in itself a finding about the gene and the disease.
oral squamous cell carcinoma (1 paper, 2010). "The distribution of GpIbα, F-actin and filamin A during cytokinesis in four cancer cell lines including HeLa, liver adenocarcinoma SK-HEP-1 and oral squamous cell carcinoma derived UPCI∶SCC40 and UPCI∶SCC103 was examined by immunofluorescence." (PMID 20520840, 2010).
oropharyngeal cancers (1 paper, 2019). Carcinoma, predominantly squamous cell, arising from the epithelial cells of the oropharynx. "A similar differential analysis in the HPV- cohort indicated a panel completely distinct from the HPV+ oropharyngeal cancers; FADD (Fas Associated via Death Domain, 41%), FKBP9 (FKBP Prolyl Isomerase 9, 24%), FLNA (Filamin A, 24%) and DNMT3B (DNA Methyl transferase 3 Beta, 18%) with high prevalence." (PMID 31310629, 2019).
osteoarthritis (1 paper, 2024). A noninflammatory degenerative joint disease occurring chiefly in older persons, characterized by degeneration of the articular cartilage, hypertrophy of bone at the margins and changes in the synovial membrane. "Such a small molecule, kartogenin, binds to FLNA, disrupting its interaction with the transcription factor core-binding factor β subunit (CBFβ), and induces chondrogenesis by regulating the CBFβ-RUNX1 transcriptional program in osteoarthritis." (PMID 39195282, 2024).
Pick disease (1 paper, 2023). A rare neurodegenerative disorder leading to dementia. "In a previous study, FLNA was found to co-localize with Tau aggregates in AD, FTLD-Tau, Pick’s disease, and PSP using immunocytochemistry." (PMID 36399251, 2023).
pneumonia (1 paper, 2020). An acute, acute and chronic, or chronic inflammation focally or diffusely affecting the lung parenchyma, caused by an infection in one or both of the lungs (by bacteria, viruses, fungi, or mycoplasma.). "Here we report a female patient with FLNA mutation, who presented with recurrent pneumonia, arterial septal defect (ASD), mild developmental delay and rapidly progressive PAH." (PMID 33143682, 2020).
polycystic kidney disease (1 paper, 2017). A usually autosomal dominant and less frequently autosomal recessive genetic disorder characterized by the presence of numerous cysts in the kidneys leading to end-stage renal failure. "We have previously demonstrated that during pathological conditions such as polycystic kidney disease, polycystin 2 (TRPP2) inhibits the activity of potassium-selective MSCs through a filamin A-mediated cytoskeletal effect, and renders tubular epithelial cells susceptible to apoptosis." (PMID 29234037, 2017).
postmenopausal osteoporosis (1 paper, 2022). Metabolic disorder associated with fractures of the femoral neck, vertebrae, and distal forearm. "A report suggests that negative regulation of FLNA in mice is age-related and postmenopausal osteoporosis in vitro osteogenic differentiation in OP promotes RANKL-induced osteoclast differentiation." (PMID 36311708, 2022).
progressive supranuclear palsy (1 paper, 2023). A rare late-onset neurodegenerative disease characterized by supranuclear gaze palsy, postural instability, progressive rigidity, and mild dementia. "Again, genetic variations and protein abundance of FlnA induce tau aggregation and tau pathologies causing neurodegeneration and progressive supranuclear palsy." (PMID 38040692, 2023).
prolactinomas (1 paper, 2025). "Additionally, molecular markers including DRD2 gene variants, altered expression levels of PRDM2, Filamin A, or PRB3, and dysregulated TGF-β1/Smad3 signaling pathways offer insights into the molecular pathogenesis of aggressive prolactinomas." (PMID 41013821, 2025).
proteopathy (1 paper, 2017). "This third proteopathy is an altered conformation of the scaffolding protein FLNA." (PMID 34295950, 2017). "Hence, the FLNA proteopathy might also disrupt synaptic and dendritic function in AD by disrupting actin dynamics." (PMID 34295950, 2017). "Hence, unlike the proteopathies of tau and alpha-synuclein, the altered conformation of FLNA is not due to changes in phosphorylation state." (PMID 34295950, 2017).
psoriasis (1 paper, 2025). An autoimmune condition characterized by red, well-delineated plaques with silvery scales that are usually on the extensor surfaces and scalp. "Venn diagram analysis revealed four overlapping genes, SLC3A2, GYS1, FLNA, and FLNB, which may serve as core candidates linking disulfidptosis to the molecular mechanisms of psoriasis." (PMID 41224720, 2025).
renal cell carcinoma (1 paper, 2019). "Furthermore, weak FLNA expression was shown to correlate with a poor prognosis in patients with nasopharyngeal, gastric, and renal cell carcinomas." (PMID 31681605, 2019).
renal cystic dysplasia (1 paper, 2019). "Moreover, a zebrafish ciliopathy model of Meckel-Gruber syndrome (in which symptoms include renal cystic dysplasia) demonstrated the importance of the zebrafish paralogues meckelin (mks3) and filamin A (flna) in causing the disease." (PMID 29502161, 2019).
rheumatic diseases (1 paper, 2017). "N-Acetyl-glucosamine-6-sulfatase (GNS) and filamin A (FLNA) were identified as autoantigens that produce responses from both T and B cells, in over 50% of RA patients, but not in healthy controls or patients with other rheumatic diseases." (PMID 28948174, 2017).
rheumatoid arthritis (1 paper, 2022). A chronic, systemic autoimmune disorder characterized by inflammation in the synovial membranes and articular surfaces. "Another example of molecular mimicry involves the rheumatoid arthritis (RA)-relevant autoantigens N-acetylglucosamine-6-sulfatase (GNS) and filamin A (FLNA)." (PMID 35572569, 2022).
sarcopenia (1 paper, 2025). Progressive decline in muscle mass due to aging which results in decreased functional capacity of muscles. "Correspondingly, the sarcopenia model showed marked differential expressions of BCL6, DDIT4, FLNA, FOXO1, NFKBIA, PGK1, and STAT3." (PMID 41282482, 2025).
scoliosis (1 paper, 2020). A congenital or acquired spinal deformity characterized by lateral curvature of the spine. "MNS is caused by gain-of-function mutations in the FLNA gene (OMIM: #30017) which encodes filamin A. Patients with MNS typically have unusual facial features, short ribbon-like ribs, scoliosis, bowing of the long bones, and vertebral scalloping." (PMID 32814550, 2020).
serous ovarian cystadenocarcinomas (1 paper, 2022). "Amongst the proteomics identified and validated genes, the expression of TGFBI significantly positively correlated with the expression of GFPT2, FLNA, G6PD, ITGAV, ITGA1 and ITGA2 within the serous ovarian cystadenocarcinomas in TIMER database." (PMID 36463238, 2022).
short bowel syndrome (1 paper, 2025). "Additionally, two cases of isolated congenital short bowel syndrome carrying mutations affecting the long isoform of FLNA were reported by Van Der Werf and Wang." (PMID 40860336, 2025).
somatotropinomas (1 paper, 2019). "Filamin-A (FLNA) plays a crucial role in somatostatin receptor (sst) subtype-2 signaling in somatotropinomas." (PMID 30718563, 2019). "Therefore, our current and previous data suggest that FLNA participates in the process of sst2 regulation and signaling in somatotropinomas." (PMID 30718563, 2019). "Notably, FLNA was expressed at the membrane and cytoplasmic levels but not at the nuclear level in our cohort of somatotropinoma samples." (PMID 30718563, 2019). "Therefore, the exact role of FLNA in somatotropinomas is not certain, and further studies are needed to better understand its connection to sst2, sst5 and D2 and its association with pharmacological treatment using drugs targeting these receptors, such as pasireotide and cabergoline." (PMID 30718563, 2019).
subependymal nodular heterotopia (1 paper, 2022). "Subependymal nodular heterotopias have been described in patients with chromosomal rearrangements, as well as associated with intragenic gene mutations (e.g., in FLNA, ARFGEF2, DCHS1, FAT4, ERMARD, and NEDD4L)." (PMID 35585091, 2022).
urofacial syndrome (1 paper, 2022). "Several monogenic causes of other congenital bladder outflow obstruction disorders have been described including BNC2 in urethral stenosis; FLNA in syndromic urethral anomalies; HPSE2 and LRIG2 in urofacial syndrome; CHRM3 in prune-belly like syndrome; and MYOCD in megabladder." (PMID 36124557, 2022).
tumor (116 papers, 2008 to 2026). "Our data substantiates the notion of a bivalent role for FLNA, consistent with other reports that discuss its multifaceted involvement in cancer, where it has been implicated in both tumor-promoting and tumor-suppressive signaling." (PMID 41317652, 2026). "Several studies have shown how the increased expression of FLNA is associated with neurological disorders, tumor development, and decreased survival rates." (PMID 40004522, 2025). "Upregulation of G2/M Wee1 kinase was shown in FLNA‐deficient mouse neural progenitor cells, and it has been reported in several tumours." (PMID 39528354, 2025). "When located in the cytoplasm, full-length FLNA promotes tumor formation by interacting with signaling molecules that are closely linked to tumor invasion and metastasis." (PMID 38584831, 2024). "Several studies have demonstrated that loss of FLNA disrupts the arrangement of the F-actin cytoskeleton and impairs cell motility in tumor cells." (PMID 39399465, 2024). "Due to its significant roles in cytoskeletal remodelling affecting cell adhesion, migration, mitosis and signalling, filamin A is implicated in cancer pathophysiology, and particularly tumour cell metastasis." (PMID 38958472, 2024). "Very recently, the protumorigenic and antitumorigenic role of filamin A is also discussed regarding its intracellular localization: high levels of filamin A in the cytoplasm are associated with tumor-promoting cell behavior." (PMID 28231263, 2017). "Various other studies have demonstrated an association between FLNa overexpression and tumor metastasis in several types of cancer." (PMID 24137390, 2013). "In addition, the expression of FLNA was associated with a less aggressive tumour behaviour in ACCs." (PMID 38068896, 2023). "Overexpression of FLNA reversed the cytoskeleton remodeling-related suppression of tumor metastasis in ARHGAP21-knockdown HCC cells." (PMID 41957357, 2026). "Our findings reveal a functional equilibrium between the tumor-suppressive DLC1-FLNA and oncogenic MRTF-A-FLNA complexes, controlled by FLNA phosphorylation at serine 2152 (FLNA pSer2152)." (PMID 41317652, 2026). "In many ACC cases, expression of the cytoskeletal protein filamin A (FLNA) is dramatically reduced; its presence in a tumour is associated with less aggressiveness." (PMID 39528354, 2025). "Particularly, FLNA appeared to be a potential “protective” factor for ACC aggressiveness as its presence, although at low levels, was associated with a less aggressive tumour behaviour (lower ENSAT stage, Weiss score, and S‐GRAS score)." (PMID 39528354, 2025). "Rab4 and filamin-A affected furin function and localisation under hypoxia and promoted tumour invasion." (PMID 40293576, 2025). "These examples of interaction in multiple human cancers identify FLNA as an important regulator of tumor cell signaling and growth, and thereby make FLNA attractive in developing novel strategies to stop or at least to slow the growth of human tumors." (PMID 39195282, 2024). "The tumor-suppressive role of the TGF-β-mediated FlnA/R-Smad signaling pathway is observed in normal prostate epithelial cells (S. Assinder and Cole, 2011)." (PMID 39055653, 2024). "Here, filamin A switches between tumour suppressive or oncogenic roles dependent on the specific cancer as well as cellular localisation of filamin A." (PMID 38958472, 2024). "Several studies have evidenced that filamin A cleavage is a double-edged sword in the promotion or repression of cancer metastasis in a tumour tissue-dependent context." (PMID 38958472, 2024). "Filamin A ubiquitination is additionally key to Natural Killer (NK) cell migration to the tumour microenvironment, controlled by the aryl-hydrocarbon receptor (AHR)." (PMID 38958472, 2024). "These mice were then used to functionally validate the role of Filamin A editing in both tumor and ischemia models." (PMID 38192612, 2024).
tumor (continued). "Lymphocyte genes in MM samples which were very downregulated compared to those in HC samples included MYH9, RN7SL2, ACTB, AHNAK and FLNA, which play important roles in cell motility, cell structure, cell migration and tumour metastasis." (PMID 37914759, 2023). "In the literature, the role of FLNA expression in the OS of patients varies according to the type of tumours." (PMID 38068896, 2023). "We therefore identify filamin A editing as a critical component for angiogenesis, tumor growth, and metastasis formation." (PMID 36457700, 2022). "Several studies show that FLNA regulates cell migration and tumour invasion by controlling focal adhesion turnover." (PMID 35124883, 2022). "Due to its crucial importance in cell migration and adhesion, FLNA was originally discovered as a tumor-promoting factor, closely involved in tumor invasion and metastasis." (PMID 37435454, 2022). "For instance, in RAS-induced lung tumorigenesis, knockout of FLNA significantly reduced the tumor formation and proliferation of fibroblasts via inactivation of ERK and AKT." (PMID 34485398, 2021). "Nevertheless, in contrast to FLNA, FLNB deficiency enhanced RAS-induced tumor growth and metastasis through the RAS/ERK pathway." (PMID 34485398, 2021). "When localized to the cytoplasm, filamin A has a tumour-promoting effect by interacting with signalling molecules." (PMID 34771736, 2021). "It has been reported that Filamin A inhibits tumor growth and metastasis by interacting with transcription factors when the active cleaved form of Filamin A localizes to the nucleus." (PMID 34001900, 2021). "For example, many genes involved in the modulation of the androgen receptor function were inhibited in the LNCaP xenograft tumor, including Hsp90AA2P, FLNA, and FKBP4." (PMID 33808801, 2021). "In turn, FlnA (filamin A) binds signaling molecules, whereas its nuclear localization acts as a tumor suppressor through regulation of the transcription factors." (PMID 33036298, 2020). "We also observed a decrease in the Filamin A expression in primary tumor and metastatic samples in Taylor's cohort." (PMID 30623593, 2019). "Numerous studies have shown FLNA is directly related to the EMT of tumor cells, mostly, the phosphorylation of FLNA determined its molecular biology function." (PMID 31632499, 2019). "We provide the first evidence for filamin A carbonylation that can be used for follow-on investigations into how its carbonylation, and potentially site-specific carbonylation, impacts its tumor-promoting function." (PMID 29596499, 2018). "If filamin A undergoes proteolysis, the C‐terminal fragment is localized to the nucleus and acts to inhibit tumor growth." (PMID 29862660, 2018). "One tumor contained a cluster of highly mutated genes (bottom left), including SPARC and FLNA, which are associated with cell-matrix interactions and cell motility, and thus possibly involved in metastasis." (PMID 30083469, 2018). "In our study, we observed high expression and carbonylation of filamin A in tumor compared to adjacent healthy tissue." (PMID 29596499, 2018). "Among these were several genes with known tumour suppressor activity (e.g. FLNA, FBLN1, MYL9, CLIC4 and SEC23A)." (PMID 27124473, 2016). "It has been shown that Filamin A (FLNA) exerts anti-tumour activity via at least three different mechanisms." (PMID 27124473, 2016). "As cell motility or migration is one of the key steps for tumor cells metastasis, regulation on the binding capability of filamin A on integrin and actin network certainly will influence the disease progression of the cancer patients." (PMID 25944616, 2015). "This bidirectional PAK1/FLNa interaction has been demonstrated to influence actin cytoskeletal structures and enhance tumor cell migration." (PMID 26009991, 2015). "Further study showed that three of the genes, FLNA, KHSRP and HCFC1, also functioned in vivo, and knocking them down caused multifocal tumor in a mouse model." (PMID 23593504, 2013).